EGFR (epidermal growth factor receptor)
Diseases named in the same sentence as EGFR in open-access papers (continued):
Sharing a sentence is not in itself a finding about the gene and the disease.
glioma (continued). "In summary, our results demonstrated that up-regulation of miR-148a-3p by U251 cells-derived exosomes inhibited the ERRFI1 expression, so as to activate the EGFR/MAPK signaling pathway, thereby promoting glioma cell growth and angiogenesis in vivo." (PMID 33117083, 2020). "We have previously shown that EGFR inhibition by PD153035 and erlotinib protects glioma cells from hypoxia-induced cell death." (PMID 33092032, 2020). "EGFR is a well-accepted kinase that plays key roles in glioma cell proliferation and migration and SH3KBP1 activates EGFR signaling." (PMID 33643898, 2020). "EGFR is a member of the Erb family of RTKs regulating EGFR/NEAT1/EZH2 axis, and is critical for glioma cell growth and invasion." (PMID 32001707, 2020). "In the co-culture system, our data demonstrated that glioma cells-derived exosomal miR-148a-3p down-regulated ERRFI1 and activated the EGFR/MAPK signaling pathway, so as to promote cell proliferation and angiogenesis." (PMID 33117083, 2020). "The interrelationships between EGFR and miR-200 family are poorly understood, and EGF/EGFR signaling has been suggested to regulate the aggressiveness of glioma cells by modulating the miR-200 family member’s expression." (PMID 33396457, 2020). "The TMZ + BIP group showed significantly reduced expression levels of p-EGFR and p-MET in glioma tissues by IF and IHC assays." (PMID 32001707, 2020). "For instance, via the use of combined genetic and pharmacologic interventions (e.g., gefitinib, erlotinib, lapatinib and cetuximab), it was discovered that EGFR-associated gliomas were not responsive to EGFR tyrosine kinase inhibitors, but could inhibit EGFR-related autophosphorylation." (PMID 35582224, 2020). "The crosstalk signaling molecules of EGFR and MET pathways (p-AKT, p-p38, p-STAT3 and p-p65) were also mitigated by BIP-MPC-NP in TMZ-resistant glioma cells." (PMID 32001707, 2020). "In the independent experiments we observed marked reductions of EGFR, ERK-1,2 and AKT-1,2 transcript in glioma cells in response to miR-4731 infection." (PMID 33369441, 2020). "Collectively, EGFR- and VEGF-targeted therapies seem to contribute little to the treatment of gliomas in current situations." (PMID 31221203, 2019). "Established teratomas and glial tumors were harvested 3 days post CAR T cell injection and analyzed by immunohistochemistry for T cell infiltration and activation in EGFR-positive regions of teratoma." (PMID 31903167, 2019). "Both erlotinib and Roscovitine treatments markedly inhibited TRIM59 nuclear translocation, p-STAT3, PIM1 mRNA expression, and glioma sphere formation, but increased mH2A1 protein levels, validating our observations in LN229/EGFR GBM cells." (PMID 31488827, 2019). "By employing a co-immunoprecipitation (“Co-IP”) assay, we show that Ninj2 immunoprecipitated with EGFR, PDGFRβ and FGFR in A172 cells and primary human glioma cells (“P1/P2”)." (PMID 31794427, 2019). "It has been reported that KLHDC8A overexpression in human gliomas that become resistant to epidermal growth factor receptor (EGFR) silencing (a commonly used anticancer therapeutic approach), allows tumours to maintain aggressiveness through an unknown EGFR-independent pathway." (PMID 30982898, 2019). "The affibody tracer ABY-029, directed toward EGFR and conjugated site-specifically with IRDye800CW via a C-terminal cysteine, is currently undergoing clinical translation for FIGS in glioma, head and neck cancer and soft tissue sarcoma." (PMID 31139085, 2019). "Recent findings indicate a truncated and oncogenic form of the epidermal growth factor receptor (EGFR), known as EGFRVIII, which can be transferred between glioma cells by EVs." (PMID 31795140, 2019). "Our results suggest that fully activation of the oncogenic RTKs (EGFR, PDGFR and FGFR) signaling requires Ninj2 in glioma cells." (PMID 31794427, 2019).
glioma (continued). "RTKs, including EGFR (epidermal growth factor receptor), PDGFRβ (platelet-derived growth factor receptor β), and FGFR (fibroblast growth factor receptor), are key therapeutic targets of glioma." (PMID 31794427, 2019). "In glioma in vitro models, IPA induces EGFR ubiquitination through the upregulation of c-Cbl, an E3 ligase belonging to RING—domain ligase family such as SCFFBXW7 and RNF20." (PMID 31569395, 2019). "The mutation status of the isocitrate dehydrogenase (IDH) gene and the amplification of platelet-derived growth factor receptor (PDGFR) and epidermal growth factor receptor (EGFR) is of importance in the diagnosis and prognosis of glioma." (PMID 31824268, 2019). "For instance, the expression of EGFR—a common PMT inducer—was much higher in adult GBM compared to pHGG, suggesting a more limited role of this signaling in pediatric glioma than in the adult counterpart." (PMID 31614588, 2019). "We report consistent regression of orthotopic glioma in xenograft mouse models treated with EGFR806-CAR T cells, with an overall response comparable to other EGFR-directed CAR T cells (Erbitux-CAR, EGFRvIII-CAR, Nimotuzumab-CAR) on glioma xenografts." (PMID 31903167, 2019). "In any case, these results suggest that mutations in the EGFR leading to activated EGFR signaling, in more quiescent or in more proliferative NSCs of the human SVZ, may result in the migration of SVZ cells into the parenchyma and subsequent generation of gliomas or other brain tumors." (PMID 31482066, 2019). "In fact, in U87 and U251 cells the knocking down of GOLPH3 enhances EGFR endocytic trafficking, implying that GOLPH3 promotes the tumorigenic phenotype of these glioma cells by inhibiting the endocytosis and degradation of EGFR." (PMID 30779783, 2019). "For instance, BRAF 35, EGFR 36, EZH2 37, MET 38 and mTOR 39 have been reported as potential protein targets for glioma treatment." (PMID 31523189, 2019). "EGFR amplification was more frequently detected in IDH-wildtype gliomas, both, GBM (38%) and astrocytomas (43%), compared to IDH-mutant gliomas (11 and 4%, respectively)." (PMID 31623593, 2019). "VEGF receptors, epidermal growth factor receptors (EGFR) and platelet-derived growth factor receptor (PDGFR), provide a chance for glioma targeting drug delivery." (PMID 30304861, 2018). "The EGFR signaling pathway, including activation of STAT3 and increased expression of STAT3 target genes, plays an important role in glioma development." (PMID 30587839, 2018). "For example, isocitrate dehydrogenase (IDH), epidermal growth factor receptor (EGFR), and neurofibromatosis type 1 (NF1) have been the center of attention in glioma genesis." (PMID 30405856, 2018). "Most strikingly, the expression of EGFR and ERBB2—two commonly targeted RTKs in the treatment of glioma—was much higher in adult GBM compared to pHGG and DIPG." (PMID 29164272, 2018). "Determining the relative contribution of EGFR/PDGFRA transactivation to glioma signaling is complicated by the prevalence and heterogeneity of expression of both receptors in gliomas." (PMID 28831081, 2017). "ABT-806, the parental antibody of ABT-414, was found to accumulate specifically in the tumor in both mouse models and in patients with glioma and showed impressive antitumor activity in GBM xenografts harboring EGFR amplification or EGFRvIII." (PMID 29371993, 2017). "Using real-time quantitative PCR assay, we demonstrated that copy number of EGFR, HER2, HER3 and HER4 in glioma patients was significantly increased compared to control subjects." (PMID 29190914, 2017).
glioma (continued). "EGFR amplification in undifferentiated and differentiating NHNP cells, point to neural progenitor cells at the originating of glioma stem-like cell samples." (PMID 28415661, 2017). "In a mouse model, glioma cells were injected in the brain and 2 weeks later nanoparticles (gold nanorods, GNR) labeled with anti-EGFR antibodies were injected intravenously." (PMID 27878374, 2017). "Epidermal growth factor receptor (EGFR) is a cell-surface receptor overexpressed in many cancer types, including glioma." (PMID 27878374, 2017). "We have previously shown that feedback activation of EGFR is one way in which BRAFV600E glioma respond and escape from BRAFV600E glioma inhibitor treatment." (PMID 27611946, 2017). "IR enhances MMP-2 transcription and protein secretion by activating the EGFR/p38/Akt and EGFR/PI3K/Akt signalling pathways, which enhance the invasion of glioma cells." (PMID 28137309, 2017). "Its members including EGFR, HER2, HER3 and HER4 have been reported to be frequently amplified in different types of cancer including gliomas." (PMID 29190914, 2017). "In fact, it was recently observed that the IGFBP2-neutralizing antibody leads to a reduction in the levels of phosphorylated EGFR, STAT3, and AKT in human glioma cells." (PMID 28036255, 2017). "STAT3 is a downstream effector of EGFR, activated in 60% of GBM patients, promotes progression in animal models of glioma, and negatively correlates with survival." (PMID 29129908, 2017). "It is known that epidermal growth factor receptor (EGFR), PDGFR, and Met (hepatocyte growth factor receptor, HGFR) are expressed in glioma." (PMID 29161257, 2017). "Thus targeting EGFR signaling could be a promising way to radiosensitize human glioma." (PMID 28754127, 2017). "However, EGFR amplification was not predictive of survival in glioma treated with an inhibitor of EGFR concurrently with chemo and radiation therapy, and supporting evidence is limited for the role of EGFR-encoding DM in GBM recurrence following frontline radiotherapy." (PMID 29113349, 2017). "We observed increased DNA methylation in EGFR, ERBB2, ERBB3, FGFR3, and PDGFRB in IDH-mutant gliomas as the mean methylation of each gene was statistically greater than that of IDH-wildtype." (PMID 27852048, 2017). "In the present study, results from the IHC and IB analysis suggested that upon sustained release from the nanoformulation, DIM inhibited EGFR pathway activation in both SSTR2 and EGFR overexpressed rat glioma samples." (PMID 29029435, 2017). "Taken together, these data support the role of EGFR/H3K23ac/TRIM24/STAT3 signaling in the pathophysiology, clinical progression, and aggressiveness of human gliomas." (PMID 29129908, 2017). "To further assess which genes are co-upregulated by EGFR and TRIM24 in glioma cells, we identified 35 genes that were significantly reduced by TRIM24 knockdown and upregulated by EGFRvIII in LN229 GBM cells (fold change >2, p < 0.05)." (PMID 29129908, 2017). "EGFR, also targeted by lapatinib and afatinib, is a driver of LUSC and lower grade glioma (LGG) in the brain." (PMID 28719033, 2017). "In conclusion, gene amplifications specifically gene amplifications of DDB1, EGFR, MDM4 and GFAP can provide information about the cell types and the degree of heterogeneity at the origin of glioma stem-like cells." (PMID 28415661, 2017). "Concomitantly, the mean EGFR, ERBB2, FGFR3, and PDGFRB mRNA levels were statistically lower than those of IDH-wildtype gliomas, which also exhibited a marked increase in EGFR and ERBB2 protein abundance." (PMID 27852048, 2017).
glioma (continued). "While genetic alterations such as EGFR amplification and CDKN2A deletion are common in IDH1 WT gliomas, they rarely occur in gliomas with mutant IDH1." (PMID 28178660, 2017). "Using a Dox-inducible system, we examined the impact of restoring EHD3 expression to two glioma cell lines that express very low levels of EHD3, i.e. the U251 and U87MG cells, on the expression of EGFR." (PMID 27811356, 2016). "A point of distinction between glioma and melanoma adaptation to BRAFV600E inhibition involves EGFR." (PMID 27713119, 2016). "The genomic alterations in EGFR, PDGFRA, NF1, PTEN and PIK3CA were nearly exclusively found in the RMPAhigh gliomas." (PMID 27385209, 2016). "For example, previous studies have suggested co-activation of RTKs including EGFR and MET in GBM samples, we also see high MET expression in RMPAhigh gliomas, with about 5% of the RMPAhigh gliomas harboring MET amplification." (PMID 27385209, 2016). "EGFR is known as a key Receptor Tyrosine Kinase (RTK) and a therapeutic target in many cancers including gliomas." (PMID 27811356, 2016). "Therefore, we hypothesized that Kindlin-2 could regulate EGFR signaling in glioma." (PMID 27713156, 2016). "For example, EGFR, MET, and FGFR1 were highly expressed in 196 cell lines of carcinoma, melanoma, and glioma origin and high expression of EGFR correlated with decreased sensitivity to the MET inhibitor PHA665752." (PMID 27655711, 2016). "A close relationship between EGFR and VEGF has been postulated in angiogenesis, and indeed, EGFRvIII has shown to promote glioma angiogenesis." (PMID 26778701, 2016). "A tendency towards mutual exclusivity between the loss or mutation of NF1 and amplification or mutation of EGFR was observed using Fisher's exact tests, indicating that both types of alteration may be sufficient to activate the RAS-RAF-MEK-MAPK cascade in RMPAhigh gliomas." (PMID 27385209, 2016). "The induction of GBP1 is essential for EGFR-mediated matrix metallopeptidase-1 (MMP1) expression and glioma cell invasion in vitro and in vivo." (PMID 26848767, 2016). "Little is known about LRIG2, although it has been shown to be permissive for glial tumour growth in vivo, and in a glioma cell culture model, LRIG2 interacts with epidermal growth factor receptor and modulates intracellular signalling." (PMID 26315301, 2016). "While glioma cell-derived CSF1 plays a critical role for the differentiation and survival of TAMs, TAM derived EGF may contribute to the high EGFR signaling in the gliomas cells, even in the absence of mutations within the EGFR gene or amplification of this region." (PMID 27385209, 2016). "Our data are consistent with those obtained by studying human BRAFV600E mutant glioma cell lines, which point to re-activation of MAPK pathway and increased AKT and EGFR signaling activity as a mechanisms of adaptation and resistance to BRAFV600E inhibition." (PMID 27713119, 2016). "We treated mice bearing a BRAFV600E heterozygous mutant pediatric glioma, BT40, with BRAFV600E specific inhibitor PLX4720 (10 mg/kg), EGFR inhibitor HKI-272 (40 mg/kg), or a combination of PLX4720 (10 mg/kg) and HKI-272 (40 mg/kg) for 14 days." (PMID 26023796, 2015). "Thus, taking advantage of PARP inhibitor-induced cell death in PTEN-mutant glioma cells prone to genomic instability, and disabling survival pathways through EGFR and PARP inhibition, could be therapeutically exploited in the treatment of this malignant tumour." (PMID 25576921, 2015). "Here, we showed that in adult and pediatric glioma cells, inhibition of BRAFV600E results in feedback activation of EGFR that reduces the extent and duration of MAPK pathway inhibition." (PMID 26023796, 2015). "Some of the documented mechanisms include the acquisition of secondary EGFR point mutations, co-activation and/or amplification of other receptor tyrosine kinases (RTKs), and up-regulation of drug efflux pumps, however, mechanisms of resistance that are unique to glioma are not clearly defined." (PMID 25978031, 2015).
glioma (continued). "Next, fluorescent probes targeting five markers for glioma cells (termed STEAM: Sox2, Tubulin beta-3, EGFR, A2B5, c-Met) were introduced." (PMID 25720744, 2015). "PLX4720 treatment increased EGFR phosphorylation, and also activated downstream effectors MEK and ERK, in all three BRAFV600E glioma cell lines, as early as 1 hour post-PLX4720 treatment." (PMID 26023796, 2015). "For example, the hyper-methylation statuses of EGFR and methyl-guanine-DNA methyltransferase (MGMT) have been shown to play vital roles in glioma progression." (PMID 26205145, 2015). "The oppositely directed expression patterns of EGFR and NOTCH1 in these two syngeneic glioma cell lines were confirmed at the protein level by immunoblotting." (PMID 26307682, 2015). "Taken together, these results illustrate that FAK promotes the aggressive traits of gliomas by acting downstream of CD151-integrin complexes and EGFR." (PMID 26377974, 2015). "The STEAM panel consisted of sex determining region Y-box 2 (SOX2), tubulin beta-3, EGFR, A2B5, and c-Met and found specifically on high-grade glioma cells." (PMID 26322014, 2015). "We demonstrated that overexpression of PTPN9 reduces EGFR phosphorylation and cooperates with BRAFV600E inhibitor PLX4720 to reduce MAPK and Akt signaling, resulting in decreased glioma cell viability." (PMID 26023796, 2015). "The glioma-related serum and plasma markers YKL-40, osteopontin (OPN) and the extracellular domain of EGFR were described to be inversely correlated with overall survival." (PMID 25720744, 2015). "A recent study has revealed that erlotinib, a tyrosine kinase inhibitor that acts on the epidermal growth factor receptor, can significantly affect the expression of the GAS5 gene in glioma cells." (PMID 25925741, 2015). "We demonstrated EGFR's unfavorable prognostic values in a subtype of gliomas expressing a low level of EFEMP1, which was consistent with EFEMP1's anti-EGFR function." (PMID 26307682, 2015). "Our prognosis study of glioma patients classified according to EFEMP1 expression level, demonstrated, for the first time, a significant unfavorable value for EGFR." (PMID 25594013, 2014). "The epidermal growth factor receptor (EGFR), a member of RTK family, is shown to play a significant role for the proliferation and neurosphere formation in glioma CSCs." (PMID 23990015, 2014). "Our results suggest possible strategies for counteracting the pro-survival signaling from EGFR to improve the therapeutic outcome of combined radiotherapy and TMZ for high-grade gliomas." (PMID 24418474, 2014). "Cox proportional hazards regression analysis was then carried out using both log-scaled ratios of EFEMP1 and EGFR vs ACTB (continuous variables) and dichotomized variables for these 166 gliomas." (PMID 25594013, 2014). "In gliomas where EFEMP1 expression, and thus the anti-EGFR effect of EFEMP1, was suppressed, heightened levels of EGFR expression were associated with unfavorable patient outcomes in prognostic models." (PMID 25594013, 2014). "U87 glioma cells were first infected with lenti-AS-566 and then EGF was introduced to activate EGFR signaling." (PMID 24650032, 2014). "In gliomas, our data showed that EFEMP1 binding to EGFR blocked EGF-mediated activation of PI3K and MAPK signaling pathways, while in pancreatic carcinoma cells it was shown to promote these activities." (PMID 25594013, 2014). "EGFR is overexpressed in almost 40-50% of GBM and contributes to uncontrolled proliferation and survival of glioma cells." (PMID 25380967, 2014). "In a prior study, we showed that human recombinant (hr) EFEMP1 protein reduced the EGFR level and AKT phosphorylation (pAKT) in 48-hr treated glioma cell lines." (PMID 25594013, 2014). "The epithelial growth factor receptor (EGFR) overexpressed in many cancers including HNSCC, gliomas, and lung, ovarian, and pancreatic cancers is one of these targeted molecules." (PMID 24722213, 2014).